CXCR4 (C-X-C motif chemokine receptor 4)
Diseases named in the same sentence as CXCR4 in open-access papers (continued):
Sharing a sentence is not in itself a finding about the gene and the disease.
tumor (continued). "We hypothesized that the chemokine CXCL12 and its receptor CXCR4 could mediate direct interactions between GBM cells and tumor-associated endothelial cells and that disruption of this interaction might be the molecular basis for the anti-tumor effects of CXCR4 antagonists." (PMID 22427929, 2012). "CXCR4, together with its ligand CXCL12, is involved in tumor angiogenesis, directional metastasis, as well as resistance to chemotherapy and endocrine treatments for cancer therapy." (PMID 23071744, 2012). "Tumor stromal pathways are also in evidence with the common genes including; TLR4, TLR7, HLA-DRA, HLA-DQA1, CXCR4, FOS and TGFB2 (immune surveillance and chemokine pathways) and NF2, ITGA7, PGF, ITGA4, PDGFD and PARVA (focal adhesion)." (PMID 23226201, 2012). "Like CXCR4, CXCR7 is also expressed in different human cancers, including breast, being highly expressed in the tumor vasculature." (PMID 22152016, 2011). "CXCR4 is the receptor of SDF1 andis expressed on several cells such as hemato/lymphopoietic cells, stem/progenitorcells, and several tumor cells." (PMID 21304904, 2011). "Tumors with a poor prognosis in our study, such as stage III (94%), tumor size T3/T4 (82%) or SBR III (95%), had unmethylated CXCR4 (p<0.001)." (PMID 22220212, 2011). "In summary, our studies provide insight into the complexity of the contributions of CXCR4 and CXCR7 to tumor cell invasion and metastasis." (PMID 22152016, 2011). "Migration of metastatic tumor cells from the bloodstream into lymph nodes is thought to be facilitated by expression of the chemokine receptors CCR7, CXCR4 and, for B cell-derived tumors, CXCR5." (PMID 21672222, 2011). "Based on these studies, we suggest that combinations of HIF-1α, CXCR4, and VEGF expression in tumor tissue will be useful for predicting clinicopathologic significance and tumor metastasis." (PMID 20953377, 2010). "This immune gene expression signal is likely coming from tumor infiltrating immune cells; however, aberrant immune gene expression by ccRCC cells is also contributory, shown by our elevated TLR2 and CXCR4 expression data." (PMID 20502531, 2010). "The expression of CXCR4 in tumor thrombus tissue was higher than in HCC tissue, which was consistent with high expression of CXCR4 facilitating the characteristics of metastasis." (PMID 21110890, 2010). "on the other hand, CXCR4 is a membrane-bound G-protein-coupled receptor which, together with its ligand CXCL12, mediates inflammatory and tumor cell migration." (PMID 20181250, 2010). "We used immunohistochemistry to identify cells expressing CXCR1, CXCR2, CXCR3, CXCR4, CXCR5 and CCR1 in the tumour islets and stroma in 20 patients with surgically resected NSCLC." (PMID 20429924, 2010). "The positive cell ratio of CXCR4, the staining color intensity of HCC, and tumor thrombus samples were then scored." (PMID 21110890, 2010). "CXCR4 and CCR7 expression is significantly higher in patients with larger tumor size, deep stromal invasion, lymph-vascular space involvement, or lymph node metastasis." (PMID 20049170, 2010). "The interaction of CXCL12 with CXCR4 mainly affects chemotaxis, while the binding to CXCR7 mediates proliferation in tumor cells." (PMID 20049170, 2010). "Previous reports demonstrated that the expression levels of CXCR4 in different HCC tissues and tumor thrombus tissues were quite different." (PMID 21110890, 2010). "This study was conducted to investigate the expression of CXCR4 in portal vein tumor thrombus (PVTT) tissue and its possible role in the invasiveness of tumor thrombus cells." (PMID 21110890, 2010). "Together with their CXCL12 and CCL21 ligands, CXCR4 and CCR7 were significantly highly expressed in tumor cells with lymph node (LN) metastasis." (PMID 20181250, 2010). "In this study, we investigated HIF-1α, CXCR4, and VEGF expression in human colon primary tumor samples using immunohistochemistry." (PMID 20953377, 2010).
tumor (continued). "CXCR4 and SDF-1 are candidate factors that involved in the cross-talk of the tumor-niche interaction of CD44+CD24- cells." (PMID 20569497, 2010). "As shown in previous reports, univariate survival analysis showed that tumor size, lymph node metastasis, ER status, VEGF-C expression, and cytoplasmic CXCR4 expression had significant prognostic value for DFS." (PMID 19580679, 2009). "Furthermore, these results support the contention that further understanding the molecular mechanisms that are involved in the regulation of CXCR4 expression on tumor cells could lead to potential targets to modify the expression of CXCR4 on NSCLC cells and impact on metastases." (PMID 19563666, 2009). "Our data establish that hypoxia and TGF-β signaling pathways regulate tumor-secreted factors such as CXCR4 which promotes tumor cell homing to the bone, and VEGF which stimulates tumor angiogenesis and increases both osteoclast and osteoblast activity." (PMID 19727403, 2009). "HIF-1α expression was positively correlated with those of CXCR4 and CXCR7 among tumour specimens (HIF-1α-CXCR4, Spearman's r=0.55, P<0.0001; HIF-1α-CXCR7, Spearman's r=0.29, P=0.013)." (PMID 19352387, 2009). "There was an association between metastasis status and a high prevalence of certain markers including CD44+/CD24−/low, ESA+, CD133+, CXCR4+ and PROCR+ in primary tumor cells." (PMID 20027313, 2009). "Here, we show that the chemokine receptor CXCR4 stimulates the production of the chemokine CCL20 and that CCL20 stimulates the proliferation and adhesion to collagen of various tumor cells." (PMID 19340288, 2009). "In the present study, immunohistochemistry revealed that CXCR4 expression was significantly correlated with nitrotyrosine levels and lymph node metastasis in human PTC tumor samples." (PMID 18826577, 2008). "The positive cell number of CXCL12, CXCR4, MMP-2, MMP-9 and NGF expression of tumor cells in CXCL12-treated group was the highest." (PMID 18983683, 2008). "In vivo, tumour growth of N91-shRNA-CS1 and N91-shRNA-CS2 clones with reduced endogenous CXCR4 was almost totally abrogated compared to N91-pAB303 control cells." (PMID 17925864, 2007). "The specific involvement of the CXCR4/CXCL12 axis in cell proliferation, and organ-specific metastasis has been partially addressed and remains controversial in some tumour systems, including NB." (PMID 17925864, 2007). "In particular, the CXCR4/CXCL12 axis has been involved in metastasis formation, increased survival of cancer cells under harsh conditions, and establishment of a tumour promoting cytokine/chemokine network." (PMID 17925864, 2007). "Recently, the expression of CXCR4 on RCC and NSCLC tumor cells was shown to be regulated by hypoxia and the VHL/HIF-1α pathway." (PMID 17083723, 2006). "In summary, our results identified an aberrant expression of CXCR4 in NPC cells and the high level of CXCR4 expression correlated with distant metastasis and poor tumor-specific survival." (PMID 15978137, 2005). "Furthermore, combination therapy with anti‐PD‐L1 antibodies and the CXCR4 inhibitor AMD3100 activated CD8+ T cells and repressed tumor growth." (PMID 41257391, 2026). "By incorporating scRNA‐seq data from NSCLC patients, we confirmed that CXCR4 upregulation in tumor‐infiltrated CD8+ T cells is not restricted to experimental systems but is also evident in human disease." (PMID 41257391, 2026). "Indeed, pharmacological disruption of this axis using AMD3100, a CXCR4 antagonist, significantly reduced both IL-1β and CXCL12 secretion, prevented adipocyte reprogramming, and suppressed tumor cell proliferation." (PMID 42316277, 2026). "The protein levels of CXCR4 exhibited diurnal variation in tumor‐infiltrated CD8+ T cells, but not in circulating CD8+ T cells, with elevated expression observed during the dark phase (ZT18)." (PMID 41257391, 2026).
tumor (continued). "The results indicated a significant negative correlation between AZGP1 expression and tumor metastasis, while CXCR4 showed a significant positive correlation." (PMID 41535762, 2026). "Furthermore, intraperitoneal administration of AMD3100 (10 mg/kg), a CXCR4 inhibitor, to LLC1 tumor‐bearing mice resulted in the dispersal of CD8+ T cells from CAF‐dense regions throughout the tumors." (PMID 41257391, 2026). "Furthermore, chronic hypoxia, resulting from rapid tumor growth and restricted vasculature, stimulates neoangiogenesis through HIF-1α and VEGF, both of which upregulate CXCR4 expression." (PMID 40307933, 2025). "However, the expression of CXCR4+ vessel-like structures was weaker in MOC1 than in MOC2, and CXCR4 was abundantly expressed in the vessel-like structures within the tumor stroma." (PMID 41210695, 2025). "The homing mechanism is facilitated by MSC surface expression of key chemokine receptors, including CXCR4 and CCR2, which detect and respond to chemotactic gradients established by tumor-secreted factors such as SDF-1, MCP-1, and CXCL12 within the tumor microenvironment." (PMID 41301162, 2025). "Tumor cells, by expressing CXCR4, respond to CXCL12 secreted by metastatic target organs (such as lymph nodes, lungs, liver and bone marrow), thereby promoting directional migration of tumor cells." (PMID 40909292, 2025). "Additionally, hypoxia-mediated CXCR4 activation also mediates EMT and CSC persistence, both of which contribute to the drug-tolerant tumour phenotype." (PMID 41002447, 2025). "Across both tumor clusters, MDK–(ITGA4+ITGB1) and MIF–(CD74+CXCR4) emerged as prominent axes." (PMID 40948762, 2025). "formulated Sor within CXCR4‐targeted lipid‐coated poly(lactic‐co‐glycolic acid) (PLGA) NMs, modifying the NMs with the CXCR4 antagonist AMD3100 to enhance systemic Sor delivery to LC and improve tumor sensitivity to treatment." (PMID 41201063, 2025). "The use of CXCR4 inhibitor AMD3100 may be one of the strategies to reduce the interaction between CAFs and tumor cells and then improve therapeutic efficacy." (PMID 40626005, 2025). "Additionally, co-delivery of miR-126-3p mimics and miR-221-3p inhibitors via lipid nanoparticles has been shown to inhibit tumor growth and metastasis by blocking AKT and CXCR4 signaling pathways." (PMID 40607416, 2025). "Moreover, AMD3100 administration attenuated the proportions of CD206+ and CXCR4+CD206+ macrophages and GFP+ tumor cells in the HIF2A-overexpressing exosome-treated group." (PMID 40756343, 2025). "In contrast, CD8 effector cells exhibited downregulation of multiple key genes involved in tumor-suppressive transcriptional regulation (HIST1H1C, ZNF331, KLF6, and BTG1) and immune activation and trafficking (CXCR4, CD69, and TNFAIP3) in LS carriers, which was more severe in LS-CRC." (PMID 40909768, 2025). "Furthermore, we knocked down CXCR4 in SDF-1α-treated GBM cells and observed a significant reversal of stemness-related genes, tumor sphere diameter, and self-renewal potential." (PMID 41041071, 2025). "Recent research has indicated that CAFs have the potential to augment cancer stem cell (CSC) activity and promote tumor growth by activating the Wnt/β-catenin and human stromal cell-derived factor-1 (SDF-1)/C-X-C motif chemokine receptor 4 (CXCR4) signaling pathways." (PMID 40735647, 2025). "Hetero-oligomerization with CXCR4 induces negative binding cooperativity—CXCL12 binding to CXCR4 suppresses CXCL11-mediated CXCR3 activation, a mechanism implicated in tumor immune evasion." (PMID 40786052, 2025). "Similarly, engineering NSCs to express higher levels of chemokine receptors, such as CXCR4 and c-Met, augments their responsiveness to tumor-derived chemotactic signals (e.g., CXCL12, hepatocyte growth factor), thereby enhancing tumor tropism." (PMID 41264121, 2025).
tumor (continued). "Notably, CXCR4, a chemokine receptor expressed on the majority of plasma cells, interacts with its ligand CXCL12, a chemokine secreted by cells constituting the tumor microenvironment, especially the BMMSCs." (PMID 40296907, 2025). "The extensive expression of CXCR4 in cancer, coupled with the constant presence of CXCL12 in various organs, drives the activation of this axis, which in turn facilitates angiogenesis, tumor progression, and metastasis." (PMID 40142155, 2025). "Differentiation between SSR4+ and SSR4- cells suggests that SSR4 might regulate the interactions between ESCC tumor plasma cells and TME, possibly by modulating the MIF/CD74/CXCR4 axis." (PMID 40066443, 2025). "On dividing cells into SSR4-positive and -negative groups, CellChat analysis indicated that SSR4 may regulate the interactions that existed between ESCC tumor plasma cells and the tumor microenvironment (TME) by modulating the MIF/CD74/CXCR4 axis." (PMID 40066443, 2025). "The CXCL12/CXCR4 axis recruits monocytes, induces their differentiation into M2 macrophages, and promotes OSCC cell transformation into cancer stem cell (CSC)-like phenotypes, thereby accelerating tumor proliferation." (PMID 41445742, 2025). "The antitumor efficacy of MUC28z CAR-T cells has been validated both in vitro and in vivo, showing increased expression of CD25, CD11c, and PD-1, along with decreased levels of CXCR4 and CD62L, significant tumor growth reduction, and enhanced production of IFN-γ and GZMB." (PMID 40281554, 2025). "Cxcl14, a CXCR4-inhibitory ligand, localized to the outer tumor margins, whereas Cxcl16, a CXCR6 ligand important for effector T cells and ILC2s, was enriched in the tumor core." (PMID 40630529, 2025). "Moreover, S-nitrosylation blockade stimulates macrophage recruitment and promotes macrophage-mediated clearance of tumor cells by modulating “eat-me” signals through pathways involving CD47 and CXCR4." (PMID 40563669, 2025). "MIF exerts its function of promoting leukocyte recruitment to inflammatory sites by noncognate interaction with the chemokine receptors CXCR2 and CXCR4, and regulates the MIF-stimulated survival of macrophages, B cells, and tumor cells through its receptor cluster of differentiation 74 (CD74)." (PMID 39851524, 2025). "Targeting the CXCL12/CXCR4 signaling pathway by inhibiting their binding or by blocking the expression of CXCL12 can reduce the accumulation of immunosuppressive cells and enhance the anti-tumor immunity." (PMID 41376630, 2025). "In the tumor progression from non-invasive to invasive cancer, infiltration of endothelial cells (PECAM1) and macrophages (CD68) was noted in the tumor interior, in addition to increased chemokine signaling (CXCR4)." (PMID 39965034, 2025). "When these interventions were combined, tumor weight and volume were significantly reduced, supporting the hypothesis that simultaneous disruption of the CXCL12/CXCR4 axis and IL-2 modulation could reshape immune functionality within the TME." (PMID 40698080, 2025). "The SDF-1/CXCR4 axis, a central regulator of MSC chemotaxis, can be pharmacologically inhibited by AMD3100, which has been shown to significantly impair MSC homing to tumors and subsequently delay tumor progression." (PMID 40676710, 2025). "Enhancing solid tumor penetration may be achieved either by chemokine receptor engineering (CXCR4, CXCR1) to improve homing, or by altering the tumor microenvironment for improved immune infiltration." (PMID 41487532, 2025). "Incoming signals to PIAS1+ TAMs from tumor cells included elevated MIF–CD74_CD44 and MIF–CD74_CXCR4 interactions, which in this context may promote M1 polarization." (PMID 40941002, 2025). "Additionally, HMGA2 promotes tumor progression by regulating macrophage proliferation, migration, polarization and angiogenesis via CXCL12/CXCR4-dependent mechanisms." (PMID 40351420, 2025).
tumor (continued). "Additionally, treatment with β-catenin and CXCR4 inhibitors (XAV939 and AMD3100, respectively) inhibited tumor growth in mice co-injected with CAFs and PCSCs." (PMID 40735647, 2025). "Combining CXCR4 antagonists with immune checkpoint inhibitors (e.g., anti-PD-1/PD-L1), cancer vaccines, or adoptive cell therapy holds the potential to convert immunologically “cold” TNBC tumours into “hot” responsive ones." (PMID 41002447, 2025). "Furthermore, the transcription factor EWS-FLI1, characteristic of EwS, regulates the expression of both CXCR4 and CXCR7 (receptor involved in metastasis), highlighting its importance in tumor biology." (PMID 40242222, 2025). "Additionally, other CXCR4 inhibitors, such as AMD3100, are also under evaluation in clinical trials, aimed at disrupting the tumor-promoting effects of chemokines." (PMID 40134607, 2025). "PLK4 expression in the tumor tissues markedly varied with the degree of differentiation, and it was notably elevated in poor-differentiated regions compared with well-differentiated regions, wherein the expression of PHOX2B, CXCR4, and cyclin D1 was higher." (PMID 40860200, 2025). "One subpopulation expressed CD44 + CXCR3 + CXCR4 + PRF1 + and GZM family genes, while the other expressed XCL1 + NCAM1 + GNLY + and KIR family genes, suggesting that these T cells possess a robust capacity to mediate tumor cell apoptosis." (PMID 40411616, 2025). "Even without combining with chemotherapy, pharmacologic blockade using CXCR4 antagonists, such as AMD3100 (plerixafor), AMD3465, or through monoclonal antibodies, has demonstrated the ability to reduce tumour burden, delay metastasis, and enhance chemosensitivity in preclinical TNBC models." (PMID 41002447, 2025). "In line with our observations, SPHK1 expression relative to CXCR4 as well as CXCL12 relative to S1PR5 correlated positively in tumor biopsies but not in the respective normal control tissue." (PMID 40155684, 2025). "We evaluate emerging targeting approaches, including selective depletion of tumor‐promoting subsets (e.g., fibroblast activation protein+ CAFs), epigenetic reprogramming toward antitumor phenotypes, and inhibition of CXCL12/CXCR4 or transforming growth factor‐beta signaling pathways." (PMID 40656546, 2025). "CTCs exhibit the overexpression of CXCR4, while chemokine stromal cell-derived factor-1 (SDF-1, also known as CXCL12), which recruits and retains CXCR4+ cells, shows significant upregulation at the primary tumor site." (PMID 40725148, 2025). "Restriction of STAT3 signaling in CXCR4 CAR-Ts decreases the levels of TNF-α, IL-17A, and IL-6, obstructs SDF-1α expression in an NF-κB-dependent fashion, and consequently impedes the MDSC recruitment into tumor site." (PMID 41281758, 2025). "In pancreatic ductal adenocarcinoma (PDAC), CXCL12 produced by FAP+ CAFs coats tumor cells and excludes T cells; CXCR4 blockade (AMD3100) disrupts this barrier, permits intratumoral CD8+ accumulation, and synergizes with anti-PD-L1." (PMID 40940809, 2025). "BC cells secrete TGF-β, increasing recruitment of CXCR4+ monocytes to perivascular fibroblasts producing CXCL12, forming a chemotactic gradient that promotes TAM migration toward the vasculature and facilitates tumor cell intravasation and dissemination." (PMID 40868199, 2025). "The blocking of CXCR4/SDF1α via AMD3100 connected to the NPs led to a decrease in the infiltration of tumor-related macrophages, improvement in anti-angiogenesis, delay in tumor growth, and overall survival gain in orthotopic HCC mice." (PMID 40307921, 2025). "Additionally, radiotracers targeting chemokine receptor-4 (CXCR4), imaged using PET/CT, provide further opportunities for AI-assisted tumor delineation and therapy guidance." (PMID 40806525, 2025).